ADCY5 (adenylate cyclase 5)
Description:
Catalyzes the formation of the signaling molecule cAMP in response to G protein signaling. Mediates signaling downstream of ADRB1. Regulates the increase of free cytosolic Ca(2+) in response to increased blood glucose levels and contributes to the regulation of Ca(2+)-dependent insulin secretion.
Synonyms: AC5; DSKOD; FDFM
Tractability: Small molecule: a structure with a bound ligand is known; a high-quality ligand is known; it belongs to a druggable protein family. Antibody: UniProt places it where antibodies can reach, with high confidence; its Gene Ontology location is reachable by antibodies, with high confidence; UniProt predicts a signal peptide or a membrane-spanning region; the Human Protein Atlas places it where antibodies can reach. PROTAC: ubiquitination databases record sites on it; its protein half-life has been measured; a small molecule that binds it is known.
Target class: Enzyme; Lyase
Gene: Protein-coding gene on chromosome 3 (123,282,296 to 123,449,090, reverse strand). Ensembl gene ENSG00000173175.
Subcellular location: Cell membrane; Cell projection, cilium
Subcellular location (Human Protein Atlas): Plasma membrane; Vesicles; Nuclear bodies; Nucleoplasm; Primary cilium
Pathways (Reactome):
Signal Transduction: Adenylate cyclase activating pathway; G alpha (i) signalling events; G alpha (s) signalling events; G alpha (z) signalling events; GPER1 signaling; Hedgehog 'off' state; PKA activation
Metabolism: Adrenaline,noradrenaline inhibits insulin secretion; Glucagon signaling in metabolic regulation; Glucagon-like Peptide-1 (GLP1) regulates insulin secretion; PKA activation in glucagon signalling
Disease: ADORA2B mediated anti-inflammatory cytokines production; FCGR3A-mediated IL10 synthesis
Cellular responses to stimuli: High laminar flow shear stress activates signaling by PIEZO1 and PECAM1:CDH5:KDR in endothelial cells
Neuronal System: Adenylate cyclase inhibitory pathway
Transport of small molecules: Vasopressin regulates renal water homeostasis via Aquaporins
Gene Ontology:
Molecular function: adenylate cyclase activity; adenylate cyclase binding; phosphorus-oxygen lyase activity; scaffold protein binding
Biological process: adenylate cyclase-activating G protein-coupled receptor signaling pathway; cAMP biosynthetic process; cellular response to forskolin; positive regulation of cytosolic calcium ion concentration; regulation of insulin secretion involved in cellular response to glucose stimulus; cellular response to glucagon stimulus; renal water homeostasis; vascular endothelial cell response to laminar fluid shear stress; cyclic nucleotide biosynthetic process; intracellular signal transduction; system process
Cellular component: membrane; cilium; plasma membrane
Genetic constraint (gnomAD): Loss-of-function variants: 26 observed, 110.57 expected, observed/expected ratio (o/e) 0.24, 90% interval 0.17 to 0.33. The upper end of that interval is the gene's LOEUF score, 0.33, which puts it in group 1 of 6, group 1 being the genes least tolerant of losing a copy. Missense variants: 1,060 observed, 1,541.5 expected, observed/expected ratio (o/e) 0.69, 90% interval 0.65 to 0.72. Synonymous variants: 640 observed, 650.82 expected, observed/expected ratio (o/e) 0.98, 90% interval 0.92 to 1.05.
Gene-disease validity (ClinGen):
ClinGen rates the evidence that ADCY5 causes each of these diseases.
dyskinesia with orofacial involvement (semidominant): Definitive.
Homologues: Orthologues: macaque ADCY5 (99% identical), chimpanzee ADCY5 (98% identical), pig ADCY5 (96% identical), rat Adcy5 (96% identical), mouse Adcy5 (95% identical), dog ADCY5 (93% identical), guinea pig ADCY5 (78% identical), rabbit ADCY5 (76% identical), tropical clawed frog adcy5 (74% identical), zebrafish adcy5 (74% identical), Drosophila melanogaster CG43373 (44% identical). Paralogues in human: ADCY6 (64% identical), ADCY1 (36% identical), ADCY8 (35% identical), ADCY2 (33% identical), ADCY7 (32% identical), ADCY3 (31% identical), ADCY4 (31% identical), ADCY9 (26% identical), GUCY2F (15% identical), GUCY2D (14% identical), NPR2 (13% identical), NPR1 (13% identical), and 5 more.
Diseases named in the same sentence as ADCY5 in open-access papers:
ADCY5 is named in the same sentence as 93 diseases in open-access papers, as found by Europe PMC text mining. Sharing a sentence is not in itself a finding about the gene and the disease. The quoted sentences say what the papers report.
type 2 diabetes (34 papers, 2010 to 2024). "A functional regulatory variant associated with type 2 diabetes is located at the ADCY5 locus in a pancreatic islet enhancer." (PMID 38283146, 2023). "Previous genome-wide association studies of birth weight identified a variant in the ADCY5 (rs9883204) associated with birth weight and type 2 diabetes, and another variant, near CCNL1 (rs900400), associated with no obvious link to adult traits." (PMID 34267728, 2021). "Genome-wide association studies have identified adenylyl cyclase type 5 (ADCY5) as candidate gene for diabetes-related quantitative traits and an increased risk of type 2 diabetes." (PMID 33919448, 2021). "The strongest associations between type 2 diabetes risk alleles and lower birthweight are at loci that primarily affect pancreatic beta cell function (e.g. ADCY5 and CDKAL1)." (PMID 33569631, 2021). "This is contrary to what has been seen at other Type 2 diabetes loci such as ADCY5 and CDKAL1, where risk alleles in the fetus were associated with lower birth weight." (PMID 29309628, 2018). "Single nucleotide polymorphisms (SNPs) within the ADCY5 gene, which encodes adenylate cyclase 5, are associated with elevated fasting glucose and increased risk to develop type 2 diabetes (T2D)." (PMID 25793868, 2015). "Recently, two birth weight-lowering loci on chromosome 3 (near CCNL1 and ADCY5) were identified in a genome-wide association study, the latter of which is also a type 2 diabetes locus." (PMID 21712988, 2011). "Several previous GWASs demonstrated that SNPs (for example rs11708067 and rs11717195) in ADCY5 may be associated with type 2 diabetes." (PMID 36230967, 2022). "The SNPs of ADCY5 are associated with elevated fasting glucose and increased type 2 diabetes risk." (PMID 31803734, 2019). "ADCY5 is also associated with type 2 diabetes and ADRB1 with adult blood pressure." (PMID 25281659, 2015). "A majority of genes associated with type 2 diabetes from this meta-analysis (ADCY5, CDKAL1, CDKN2A/B, HHEX, IGF2BP2, SLC30A8, TCF7L2 and KCNQ1) are involved in pancreatic beta cell function, while two are implicated in insulin sensitivity (PPARG) and adiposity (FTO)." (PMID 25145545, 2014). "We also provide evidence for the first time in South Asians that alleles of SNPs in GLIS3 and ADCY5 may confer risk of type 2 diabetes." (PMID 21949744, 2011). "SNPs in ADCY5 have recently been implicated in regulation of glucose levels and susceptibility to type 2 diabetes, providing further evidence that the association between lower birth weight and/or SGA and subsequent type 2 diabetes does indeed have a genetic component." (PMID 20712903, 2010). "Adenylyl cyclase type 5 (ADCY5) has been identified as candidate gene for an increased risk to develop type 2 diabetes (T2D) in a genome-wide association study." (PMID 33919448, 2021). "Genome wide association studies revealed an association of the single nucleotide polymorphism rs11708067 within the ADCY5 gene—encoding adenylate cyclase 5—with increased type 2 diabetes (T2D) risk and higher fasting glucose." (PMID 25793868, 2015). "The potential role of ADCY5 in colorectal cancer prognosis is underscored by its methylation status and expression patterns observed in both type 2 diabetes mellitus (T2DM) and glioblastoma studies." (PMID 39678375, 2024). "We used the ‘insulin secretion’ pPS of variants in eight genes associated with type 2 diabetes risk due to poor beta cell function: MTNR1B, HNF1A, GCK, TCF7L2, TMEM258, ADCY5, SLC3OA8 and ABO." (PMID 35247066, 2022). "An example of this is type 2 diabetes GWAS SNP rs11708067 for which INFIMA analysis identified ADCY5 as the effector gene." (PMID 34425882, 2021). "Among these effector genes are ABCC8, KCNJ11, PDX1, ADCY5, and KCNQ1, which are recognized as pancreatic β-cell genes strongly associated with type 2 diabetes." (PMID 34425882, 2021).
type 2 diabetes (continued). "This SNP was shown to contribute to type 2 diabetes by disrupting an islet enhancer and, consequently, resulting in reduction of ADCY5 expression." (PMID 34425882, 2021). "Previous studies investigated in various populations the associations between the polymorphisms of the ADCY5 gene (rs11708067, rs2877716), CAPN10 gene (rs2975760, rs3792267), JAZF1 gene rs864745, and type 2 diabetes." (PMID 34440550, 2021). "Evidence from candidate gene studies, and the first GWAS of birth weight suggested that the type 2 diabetes risk alleles at the CDKAL1, ADCY5, and HHEX-IDE loci were also associated with lower birth weight." (PMID 28293907, 2017). "Furthermore, a common variation in ADCY5, a gene in the same family as ADCY3, is known to be associated with fasting plasma glucose levels and risk of type 2 diabetes." (PMID 37368776, 2023). "Previous studies have shown that polymorphisms of ADCY5, CAPN10, and JAZF1 genes may be associated with an increased risk of type 2 diabetes." (PMID 34440550, 2021). "Two meta-analysis of genome wide association studies identified two variants at adenylate cyclase 5 (ADCY5) associated with type 2 diabetes mellitus, fasting and 2-hour glucose in non-pregnant individuals of European descent." (PMID 32163478, 2020). "Additionally, there was a strong upregulation of several K+ channel genes in Aldh1b1tm1lacZ null islets, including Kcnj11, a type 2 diabetes risk factor, and expression of adenylate cyclases Adcy4 and Adcy5 was repressed." (PMID 26518685, 2016). "Of these loci, only GCK, MTNR1B, DGKB, GCKR, ADCY5 and PROX1 (besides TCF7L2 and SLC30A8) were associated with type 2 diabetes at genome-wide significance levels, with several others (but not all) showing a consistent trend but not meeting the same stringent statistical threshold." (PMID 22984506, 2012). "In addition, we provide evidence that alleles of SNPs in ADCY5 and GLIS3 may confer risk of type 2 diabetes, the first time that this has been reported in South Asian populations." (PMID 21949744, 2011). "The top-ranking pathways enriched in the shared genes include “ECM-receptor interaction” (FRAS1/SPP1, P value = 4.92e-03), “growth hormone synthesis, secretion and action” (ADCY5/SOCS3, P value = 8.84e-03) and “type II diabetes mellitus” (SOCS3, P value = 0.055)." (PMID 35606885, 2022). "Sites annotated to 10 candidate genes for type 2 diabetes, including DUSP9, BCL11A, HNF4A, and CDKN2B, and 7 candidate genes for related metabolic traits (for example, ATP11A, ADCY5 and IRS1) had differential DNA methylation in human pancreatic islets based on sex." (PMID 25517766, 2014).
diabetes (26 papers, 2012 to 2025). "Numerous studies linked Adcy5 gene polymorphisms to altered glucose metabolism, diabetes, and obesity." (PMID 34645939, 2022). "Changes in ADCY5 expression in β-cells and impaired glucose signaling represent a likely pathway through which ADCY5 gene polymorphisms affect fasting glucose levels and diabetes risk." (PMID 34440550, 2021). "In addition, increased blood glucose levels (hyperglycemia and diabetes) cause an increase of cyclic AMP by adenylate cyclase 5 in arterial myocytes, resulting in activation of L-type Ca2+ channels and vasoconstriction." (PMID 35216316, 2022). "An increased number of smaller adipocytes may link Adcy5 knockout to the previously reported effects on longevity and reduced diabetes risk, because small adipocytes are strongly related to BMI-independent retained insulin sensitivity." (PMID 33919448, 2021). "Also, a genome-wide analysis of the DNA methylation quantitative trait locus (mQTL) in human pancreatic islets revealed 383 CpGs (0.08% of tested CpGsites), showing significant associations including known diabetes loci, e.g., ADCY5, KCNJ11, HLA-DQA1, INS, PDX1 and GRB10." (PMID 38136971, 2023). "The change of ADCY5 expression in the β-cells leads to impaired glucose signal transduction, which indicates that ADCY5 gene polymorphism may affect fasting blood glucose levels and diabetes risk." (PMID 36923118, 2023). "If this assumption is true, it would turn ADCY5 into a less likely therapeutic target for the treatment of obesity and diabetes." (PMID 33919448, 2021). "Furthermore, rs11708067 is an eQTL in islets for both ADCY5 and the antisense transcript for ADCY5 supports the role of this SNP in impairment of insulin secretion in women with previous GDM, thus increasing the risk of diabetes postpartum." (PMID 34801028, 2021). "Therefore, ADCY5 has been proposed as a target for the treatment of obesity, diabetes and cardiovascular diseases." (PMID 33919448, 2021). "These rare Mendelian alleles act through gain of ADCY5 function, and this is presumably why the phenotype of this condition (familial dyskinesia with facial myokymia) does not feature diabetes." (PMID 26624892, 2015). "Similarly, genes ABCB11 (chromosome 2), ADCY5 (chromosome 3), CDKAL1 (chromosome 6), ANK1 (chromosome 8), GLIS3 (chromosome 9), and HKDC1 (chromosome 10) have been linked to various aspects of diabetes, including insulin release, glucose levels, β-cell function, and insulin resistance." (PMID 38274506, 2023). "The sample size of the PaC cases and controls without diabetes (448 cases and 557 controls), was likely underpowered as well, but our findings on DGKB-TMEM195 rs2191348, KCNQ1 rs231362, ADCY5 rs2877716 and BCL11A rs243021 may warrant further evaluation from larger studies." (PMID 25658847, 2015).
Dystonia (23 papers, 2015 to 2026). An abnormally increased muscular tone that causes fixed abnormal postures. "Variants in movement disorder genes frequently comprising dystonia as a phenotype included recurrent variants in ADCY5, C19orf12, and SLC2A1." (PMID 40533913, 2025). "Gain of function variants of ADCY5 have been associated with a broad range of movement disorders, most notably chorea, dystonia and myoclonus." (PMID 34621295, 2021). "In humans, mutations of the ADCY5 gene have been associated with early-onset autosomal dominant chorea and dystonia." (PMID 33919448, 2021). "Two out of three previously reported families with biallelic ADCY5 variants presented with a rare myoclonus‐dystonia phenotype of the ADCY5‐dyskinesia spectrum." (PMID 34631954, 2021). "ADCY5-dyskinesia is inherited in an autosomal dominant manner and causes a spectrum of clinical features including chorea, athetosis, myoclonus, dystonia, and ballistic bouts, with an onset in infancy to late-adolescence." (PMID 33488508, 2020). "We describe a family with an autosomal dominant familial dyskinesia resembling myoclonus-dystonia associated with a novel missense mutation in ADCY5, found through whole-exome sequencing." (PMID 28229249, 2017). "We report a three-generation family with ADCY5-related dyskinesia manifesting as myoclonus-dystonia, caused by a novel missense variant identified through whole-exome sequencing (WES) of a grandmother-granddaughter pair." (PMID 28229249, 2017). "Adenylyl cyclase 5 (ADCY5)-related movement disorder (ADCY5-RMD) is a rare genetic hyperkinetic movement disorder caused by pathogenic variants in the ADCY5 gene, characterized by childhood-onset chorea, dystonia, myoclonus, and distinctive paroxysmal exacerbations, often with nocturnal worsening." (PMID 41705003, 2026). "Mutations in the ADCY5 gene can cause dyskinesia and dystonia." (PMID 34824921, 2021). "Moreover, ADCY5 mutations should be considered in cases with apparent myoclonus-dystonia, particularly where SCGE mutations have been excluded." (PMID 28229249, 2017). "Besides chorea, various hyperkinetic movement disorders such as myoclonus and dystonia have been described in ADCY5 positive subjects, but the prevalence of ADCY5 mutations in such patients is unknown." (PMID 28511835, 2017). "Knockout of Kmt2b in mice forebrain results in altered expression in the dorsal dentate gyrus of a number of genes associated with dystonia including PRKRA and ADCY5." (PMID 39990802, 2025). "ADCY5 is a characteristic example, with ADCY5‐related disorders presenting with a variety of phenotypes, including paroxysmal chorea, myoclonus, and dystonia." (PMID 33816658, 2021). "In addition, loss-of-function mutations of ADCY5, the human gene encoding AC5, are responsible for chorea with dystonia, whereas gain-of-function mutations cause dyskinesia with facial myokymia." (PMID 35699413, 2022). "Additionally, they had common ADCY5‐related dyskinesia signs such as axial hypotonia, spasticity, dystonia, and limb tremor, together with infrequent features including intellectual disability, psychiatric symptoms, and cardiomyopathy." (PMID 34631954, 2021). "We performed a screening of the entire ADCY5 coding sequence in 44 unrelated subjects with genetically undiagnosed childhood-onset hyperkinetic movement disorders, featuring chorea alone or in combination with myoclonus and dystonia." (PMID 28511835, 2017). "Two further probands with milder, but overlapping, phenotypes had previously been diagnosed syndromically as autosomal‐dominant myoclonus‐dystonia and sporadic, infantile‐onset chorea without dystonia before the discovery of their novel ADCY5 mutations." (PMID 27061943, 2016). "Adenylyl cyclase 5 (ADCY5) mutations is associated with heterogenous syndromes: familial dyskinesia and facial myokymia; paroxysmal chorea and dystonia; autosomal‐dominant chorea and dystonia; and benign hereditary chorea." (PMID 27061943, 2016).
Dystonia (continued). "On the other hand, as exemplified by Patient 3, who displays mild chorea and dystonia without paroxysmal exacerbations, the absence of such manifestations, suggested as a “red flag” for ADCY5-related dyskinesias, does not rule ADCY5 mutations out, at least in the first years of life." (PMID 28511835, 2017). "Therefore, we suggest that ADCY5 gene mutations should be considered in the differential diagnosis of patients diagnosed with SGCE‐negative myoclonus‐dystonia, especially if there is axial hypotonia rather than hypertonia." (PMID 27061943, 2016). "The classical distinction is very hard to differentiate between isolated and combined dystonias since many genes have been shown to determine multiple dystonic presentations (e.g., ANO3, GNAL, ADCY5, and ATP1A3)." (PMID 36705216, 2022). "1, ADCY5), Glut1 syndrome (SLC2A1), and myoclonus‐dystonia (SGCE)." (PMID 36054588, 2022). "Importantly, the phenotypes associated with mutations in the DYT genes enriched in the putamen ‘cyan’ module belonged to different clinical subtypes of dystonia, namely isolated dystonia (ANO3 and HPCA), combined dystonia (KCTD17 and ADCY5), and paroxysmal dystonia (KCNA1, CACNA1A, PRRT2 and SCN8A)." (PMID 32889528, 2020).